CD28 (CD28 molecule)
Diseases named in the same sentence as CD28 in open-access papers (continued):
Sharing a sentence is not in itself a finding about the gene and the disease.
cervical cancer (continued). "Taken together, our results reveal the existence of two separate CD4+NKG2D+ T cell subsets defined by the co-expression or absence of CD28, the latter more likely to be present in patients with cervical cancer." (PMID 26486970, 2015). "Similarly, a negative correlation exists between CD28+ CD45RA- CD8+ T cells and the development of cervical cancer, suggesting that the immunophenotype protects against cervical cancer." (PMID 38434980, 2024). "In this urgent study, we focused our attention on the immunophenotypic characterization of CD4+NKG2D+ T cells in patients with well-established cervical carcinoma and revealed the existence of at least two separate CD4+NKG2D+ T cell subsets defined by the co-expression or absence of CD28." (PMID 26486970, 2015). "Expression of CD107a and CD161 was graphed as a percentage of gated CD4+NKG2D+ T cells in control and cervical cancer groups subdivided, in turn, into the three groups based on ranges of CD4+NKG2D+ T cell percentages, which were characterized by the expression or lack of CD28 (respectively)." (PMID 26486970, 2015).
neuroblastoma (16 papers, 2013 to 2025). Neuroblastoma (NB) is the most common solid, extracranial childhood tumor. "A Phase I trial with the 2G CE7 CAR in rotation with a similar third generation product that also includes a CD28 endodomain is currently underway at Seattle Children's Hospital for recurrent or refractory high risk neuroblastoma patients (NCT02311621)." (PMID 30459759, 2018). "Using in vitro assays, we identified a second-generation CAR structure TE9-CD8 hinge-transmembrane (H/Tm)-CD28-CD3ζ as having optimal anti-tumor effects against neuroblastoma cell lines." (PMID 36159778, 2022). "Taken together, CD28 co-stimulus was superior for inducing regression of established neuroblastoma xenografts by L1CAM-specific mouse CAR T cells, predominantly those harboring the short spacer domain." (PMID 33801448, 2021). "These GD2.CD28.IL15 CAR NKT cells that target neuroblastoma indicated encouraging results in pre-clinical cancer models and were chosen for an initial clinical trial." (PMID 35008348, 2021). "Treating patient-derived neuroblastoma xenografts with human L1CAM-targeting CAR T cells confirmed the superiority of CD28 co-stimulus." (PMID 33801448, 2021). "Using monoclonal, murine-derived L1CAM-specific CAR T cells in Rag-/- mice harboring established xenografted tumors from a human neuroblastoma cell line revealed a clear superiority in CAR T cell trafficking using CD28 co-stimulation." (PMID 33801448, 2021). "In the clinic, GD2 CARs with CD28/OX40 costimulatory domains are currently in phase I trials for neuroblastoma." (PMID 30804938, 2019). "A recent study comparing third generation GD2 CARs to treat in vivo models of neuroblastoma found 4-1BB/CD28 CARs to be superior to CD28/OX40ζ CARs in terms of activation, exhaustion, and in vivo antitumor efficacy." (PMID 30804938, 2019). "This second generation CAR with a CD28 costimulation domain controlled tumor burden in a xenograft neuroblastoma model, but had only modest effects on survival." (PMID 30459759, 2018). "A fourth generation GD2 CAR (including CD28, 4-1BB, and CD27 costimulatory domains in addition to CD3ζ) is also being tested in a multi-institutional Chinese Phase II trial for high-risk neuroblastoma patients." (PMID 30459759, 2018). "Neuroblastoma cells induced Il2 release only in CAR T cells utilizing CD28 signaling." (PMID 33801448, 2021). "Clinically, treatment with a GD2-targeting CD27/CD28 CAR-T cells yielded 15% PR and 38% SD in 34 neuroblastoma patients, with a one-year survival rate of 74% (NCT02992210 and NCT02765243)." (PMID 35053463, 2022). "We next compared CD28 and 4-1BB endodomains combined with a CD8 H/Tm by assaying effector function against B7-H3-expressing neuroblastoma cells." (PMID 36159778, 2022). "The CAR utilizing 4-1BB costimulation performed worse against neuroblastoma cells expressing low antigen levels, compared with the CAR imparting CD28 costimulation." (PMID 34771652, 2021). "This resulted in better control of tumor growth in NSG mice engrafted with the neuroblastoma tumor cell line CHLA-255 as compared to CD28 co-stimulated CAR-T cells without co-expressing LCK." (PMID 35053463, 2022). "Previously, one IgM and two IgG derived anti-GD2 CARs were tested against neuroblastoma cells either with or without costimulatory signals such as OX40, CD28 and 4-1BB." (PMID 26298772, 2015).
colon carcinoma (14 papers, 2007 to 2024). "Studies including whole population of peripheral or tumor-infiltrating T cells showed that in NSCLC and breast, cervical, and colon cancers, CD28 was downregulated while apoptotic receptor CD95 was upregulated." (PMID 29785404, 2018). "Moreover, “CD28 on CD39+ activated Treg” was causally related to stomach cancer and esophageal cancer, while “CD19 on IgD+ CD38- naive” was found to be causally related to colon cancer and cancer of the small intestine." (PMID 38533503, 2024). "Since data for esophageal cancer, gastric cancer, and colon cancer are only available in the BBJ database, we verified “CD45 on CD4+” and “CD28 on CD39+ activated Treg” only." (PMID 38533503, 2024). "For this purpose, T cells from tdLN of BALB/c mice bearing subcutaneous CT26 colon cancer tumors were isolated and stimulated ex vivo with CD3/CD28 activation beads to generate a polyclonal population of CT26 tumor antigen–reactive T cells." (PMID 35476449, 2022). "In patients with colon cancer, we found that tumor-infiltrating CD8+ T cells, as well as CD8+ T cells in peripheral blood express CD73 but CD73 expression on CD28−CD8+ T cells, is significantly increased after cell infiltration into the tumor as compared to that on CD28+CD8+ T cells." (PMID 34011962, 2021). "Intriguingly, CD8+ lymphocytes expressing CD28, the CD80 receptor, were reduced in UC patients who developed colon cancer as opposed to patients with UC and dysplasia." (PMID 25595911, 2015).
inflammatory bowel disease (13 papers, 2012 to 2025). A spectrum of small and large bowel inflammatory diseases of unknown etiology. "Core α1,6-fucose is required for the induction of TCR-anti-CD3/CD28 signalling leading to inflammation in patients with inflammatory bowel disease (IBD)." (PMID 41030447, 2025). "CARMIL2 is required for CD28-mediated co-stimulation of NF-κB signaling in T cells and its deficiency has been associated with primary immunodeficiency and, recently, very early onset inflammatory bowel disease (IBD)." (PMID 33723309, 2021). "We however did not confirm a previous result of high expression of IL-17 by CD73+ CD4+ T cells, possibly because we used PMA/Ionomycin stimulation of cells from healthy adult controls, compared to anti-CD3/CD28 stimulation of cells from inflammatory bowel disease patients in the previous study." (PMID 33477692, 2021). "It has been studied that IL-2, IL-3 and IL-8 expressions (which play an important role in intestinal inflammation such as in inflammatory bowel disease [IBD]) are regulated by NF-κB during CD28 co-stimulation." (PMID 35909996, 2022). "CD8+CD28− T cells have been shown to suppress experimental inflammatory bowel disease in mice, and repeated stimulation of human peripheral blood lymphocytes with allogeneic APCs in vitro causes a loss of lymphocyte proliferative activity, owing to the actions of CD8+CD28− regulatory T cells." (PMID 34259422, 2021).
non-Hodgkin lymphoma (13 papers, 2010 to 2025). Distinct from Hodgkin lymphoma both morphologically and biologically, non-Hodgkin lymphoma (NHL) is characterized by the absence of Reed-Sternberg cells, can occur at any age, and usually presents as a localized or generalized lymphadenopathy associated with fever and weight loss. "Two clinical trials using third-generation CARs (CD28/4-1BB/CD3ξ) have been published on leukemia and Non-Hodgkin lymphoma (NHL), respectively." (PMID 33567640, 2021). "One non-Hodgkin lymphoma cell line Raji cells co-cultured with peripheral blood-derived T cells were stably transfected with anti-CD20scFvFc/CD28/CD3zeta gene or anti-CD20scFvFc gene." (PMID 20815894, 2010). "For example, a clinical trial treating 11 patients with non-Hodgkin’s lymphoma showed that tandem of a Toll-like receptor 2 (TLR2) TIR structural domain in a CD28-based CAR structure targeting CD19 resulted in severe CRS in 2 patients (18%) and severe ICANS in 1 patient (9%) (NCT04049513)." (PMID 40181986, 2025). "In HIV-positive individuals at risk for developing non-Hodgkin lymphoma (pre-NHL), CD8+PD-1+CD27+CXCR4− T-cells positively correlate with CD4+FoxP3+PD-1+ T-cells expressing CD27, CD28, ICOS, and CD71." (PMID 41148820, 2025). "The potential superiority of CD19 3G has been suggested in a clinical trial, in which CD19 2G CAR-T-cells (CD28) and CD19 3G CAR-T-cells (CD28 and 4-1BB) were infused simultaneously in 16 patients with relapsed or refractory non-Hodgkin’s lymphoma." (PMID 37626869, 2023). "So adoptively T cells transduced anti-CD20scFvFc/CD28/CD3zeta gene mediates enhanced anti-tumor activities against CD20 positive tumor cells, suggesting a potential of gene-based immunotherapy for non-Hodgkin lymphoma." (PMID 20815894, 2010). "Although requiring the generation of two products for each individual, this study showed that the inclusion of the CD28 signaling motif supported superior activation, proliferation, and effector function of CAR-T cells in patients with CD19+ Non-Hodgkin lymphoma (NHL)." (PMID 38226627, 2024).
non-small cell lung carcinoma (13 papers, 2017 to 2025). A group of at least three distinct histological types of lung cancer, including non-small cell squamous cell carcinoma, adenocarcinoma, and large cell carcinoma. "For example, immunosuppressive CD28− CD8+ T cells expressing Forkhead box p (Foxp) 3 have been found increased in patients with non-small cell lung cancer and their frequency declines after tumor removal." (PMID 35328795, 2022). "In patients with advanced non-small cell lung cancer (NSCLC), a high number of peripheral blood circulating CD28− CD57+ KLRG-1+ CD8+ T cells is associated with a poor clinical response to PD-1 inhibitors." (PMID 35328795, 2022). "Costimulatory molecules expressed by most CD8+ TRM cell subsets are CD27 and CD28, and in non-small cell carcinoma, the CD69+CD8+ TILs express CD27 and CD28." (PMID 33467606, 2021). "In addition, CD8+/PD-1+/CD28− T cells from non-small cell lung cancer (NSCLC) patients showed a lower response to anti-PD-1 treatment as compared to CD8+/PD-1+/CD28+ T cells." (PMID 39329753, 2024). "Butyrate, a SCFA, exemplifies this mechanism by enhancing histone H3K27 acetylation at the PDCD1 and CD28 promoters in CD8+ T cells, thereby elevating PD-1 expression and amplifying anti-PD-1 therapeutic responses in non-small cell lung cancer (NSCLC)." (PMID 41394818, 2025). "Concurrently, within the memory-enriched compartment, we observed a higher frequency of the less differentiated PD1+CD28+ phenotype and fewer PD1−CD28− cells in non-small cell lung cancer (NSCLC) patients when compared to both HDs and other tumor types." (PMID 37898752, 2023). "The PD-L1 expressing human non-small cell lung cancer cell line, NCI-H2023 was co-cultured with human CD3+ T cells that were stimulated for 2 days with suboptimal concentrations of CD3, CD28, and IL2." (PMID 30563566, 2018). "Similarly, there was a trend toward lower CD122 expression on CD28+ cells that co-expressed TCF1 than on CD28- cells, which were considered to be terminally differentiated cells, among the PD-1+ CD8 TILs from human non-small-cell lung cancer." (PMID 37409128, 2023). "It has been reported that unfractionated self-peripheral blood mononuclear cells (PBMC) can be co-cultured for a long time with epithelial cell organoids from CRC or non-small cell lung carcinoma (NSCLC) in the presence of IL2, IFNγ, anti-CD3 and anti-CD28 antibodies coated to plastic for 28 days." (PMID 34298630, 2021).
T-cell lymphomas (13 papers, 2011 to 2024). "NK92 cells overexpressing a CD3-CAR containing the costimulatory domains of 4-1BB and CD28 had shown cytotoxic activity against peripheral T-cell lymphoma and T-ALL cells in vitro and reduction in tumor burden in a xenograft model." (PMID 35158792, 2022). "Approximately 13% of T-Cell lymphomas with a TFH origin show point mutations and translocations involving CD28, representing the most common genetic alteration in the TCR signaling pathway." (PMID 35330161, 2022). "Here, we describe a monoclonal CD8+ CD4− αβ T cell receptor Vβ2+ CD28+ T cell lymphoma line, termed T8-28." (PMID 22163033, 2011). "Conversely, no mutations were found in RHOA, IDH2, and CD28, known to occur in angioimmunoblastic T-cell lymphoma and other nodal T-cell lymphomas of T follicular helper origin." (PMID 31028364, 2020). "As for T-cell lymphomas, genetic studies have shown the correlation with reference antigens, specifically CD279/PD1, CD10, BCL6, CXCL13, ICOS, SAP, and CCR5, but also genetic abnormalities included TET2, IDH2, DNMT3A, RHOA, and CD28 mutations, or gene fusions (for example ITK-SYK or CTLA4-CD28)." (PMID 38893221, 2024). "The potential use of a third generation (CD28 and 4-1BB co-stimulatory domains) CD7-specific uCAR for the treatment of r/r T-ALL and non-Hodgkin’s T-cell lymphoma, was described." (PMID 36624522, 2023). "The expression levels of CD28 and CD40LG are tightly regulated in normal T cells, as abnormal activation or overexpression of them lead to many types of T-cell malignancies including ATLL and T-cell lymphomas." (PMID 38233409, 2024). "Clinical trials on the efficacy in T-Cell lymphoma are rare, but one case report reports a rapid clinical response with the CTLA4 inhibitor ipilimumab in a patient with Sezary syndrome harboring a highly expressed gene fusion between CTLA4 and CD28." (PMID 35330161, 2022). "Secondly, CD28 and CD40LG are two essential stimulatory molecules expressed on the surface of T cells; aberrant overexpression or activation of them contribute to many types of T-cell malignancies including adult T-cell leukemia/lymphoma (ATLL) and T-cell lymphomas." (PMID 38233409, 2024). "Since the use of anti-CD4 mAbs showed a reversible depletion of CD4+ cells in T-cell lymphoma patients without inducing immunosuppression, third-generation anti-CD4 CARs (containing 4-1BB and CD28 costimulatory domains) were then developed, demonstrating in vitro and in vivo preclinical efficacy." (PMID 36624522, 2023).
acute lymphoblastic leukemia (12 papers, 2013 to 2026). Leukemia with an acute onset, characterized by the presence of lymphoblasts in the bone marrow and the peripheral blood. "With second generation CARs, complete response rates of around 40% have been demonstrated in acute lymphoblastic leukemia (ALL) murine models treated with 5–10 × 106 CD19 CD28 or 4-1BB CAR T cells." (PMID 30470934, 2019). "An alternate domain, 4-1BB, has been proven to be superior to CD28 in certain in vivo studies that indicate CARs having CD137 have improved anti-leukemic efficacy and improved persistence in the primary human lymphoblastic leukemia xenograft model." (PMID 38534399, 2024). "Infusion of T cells expressing CAR specific for CD19 with either CD3ζ /CD28 or CD3ζ /CD137 can induce complete tumor regressions in subsets of patients with B-lineage lymphomas, acute lymphoblastic leukemia (B-ALL), or chronic lymphocytic leukemia (CLL)." (PMID 26030772, 2015). "For example, in an acute lymphoblastic leukemia preclinical model, the expression of CD28-co-stimulated CAR along with 4-1BB-L increases the persistence and tumoricidal effect of transduced effector T cells, optimizing the engagement of both CD28 and 4-1BB signals." (PMID 32670869, 2020).
glioblastoma (12 papers, 2012 to 2025). The most malignant astrocytic tumor (WHO grade IV). "With respect to CAR design, the CD28 signaling domain was preferred to 4-1BB as it confers superior effector function in several solid tumors tumor models including mesothelioma and glioblastoma." (PMID 34571983, 2021). "Combined with their research, they proved that HER-CAR NK -92 cells (2nd generation CAR, CD28) could effectively control the tumor progression in the mouse models of HER2+ glioblastoma." (PMID 36032149, 2022). "generated B7-H3-redirected chimeric antigen receptor (CAR) (B7-H3.CAR) T cells encoding CD28 or 4-1BB endodomains and CD19-redirected CAR (CD19.CD28) T cells as control and tested them with U87MG and U138MG glioblastoma cells." (PMID 39664380, 2024). "PBMCs and living or ferroptotic glioblastoma cells were co-cultured with or without apyrase in the presence of a CD3/CD28 activator." (PMID 41300529, 2025). "Notably, an enrichment of CD28− CD8+ T cells, besides going along with T cell immunosenescence, was also found in patients with glioblastoma (GBM)." (PMID 35328795, 2022). "The research showed that in the mouse models, HER2-CAR NK -92 cells (2nd generation CAR, CD28) could specifically recognize and kill HER2+ glioblastoma cells and induce endogenous anti-tumor immunity." (PMID 36032149, 2022).